HIF1A (hypoxia inducible factor 1 subunit alpha)
Diseases named in the same sentence as HIF1A in open-access papers (continued):
Sharing a sentence is not in itself a finding about the gene and the disease.
tumor (continued). "Interestingly, pyruvate kinase M2 (PKM2) and HIF-1α can bind directly to hypoxia response element (HRE) sites on the PD-L1 (programmed death-ligand 1) promoter to upregulate PD-L1 expression by macrophages and promote tumor growth by restraining CD8+ T cell responses." (PMID 33670082, 2021). "Thus, AIM2 in NSCLC exerts tumor‐promoting effects in an inflammasome‐dependent manner and regulation of mitochondrial dynamics, presumably triggering an IL‐1β/STAT3 response by the nuclear factor‐κB (NF‐κB)/COX‐2/HIF‐1α pathway and contributing to the MAPK/ERK pathway activation." (PMID 34014039, 2021). "Besides, as the tumor grows larger, the core becomes hypoxic, resulting in hypoxia-induced upregulation of pro-angiogenic factors such as vascular endothelial growth factor receptor (VEGFR) 1–3 and stabilization of hypoxia-inducible factor-1α (HIF-1α) activity." (PMID 33836774, 2021). "Though HIF-1α does not always fit the overall effect of hypoxia, it is the major factor that widely affects the tumor microenvironment, including the expression of numerous genes in tumor cell progression and metastasis, upregulation of VEGF, and epithelial–mesenchymal transition." (PMID 34504845, 2021). "In contrast, HIF-1α stability may depend on high levels of reactive oxygen species (ROS) in hypoxic cancer cells, which can activate the NF-κB, TNF-α and STAT3 signaling pathways in inflammatory cells and tumor cells to release a variety of inflammatory cytokines involved in changes in the TME." (PMID 33856653, 2021). "However, in our study, when we measured the markers of TAMs, including HIF-1α, CCL2, and PECAM1, we found that gemcitabine treatment potently activated the expression of TAM markers, while knockdown of IFI16 reversed the increase in TAMs in the tumor microenvironment." (PMID 34150748, 2021). "Furthermore, other mechanisms including a lack of drug induced senescence in hypoxic tumor cells, induction of autophagy by hypoxia, and driving an immunosuppressive phenotype through HIF-1α, have been proposed to contribute to hypoxia mediated chemotherapy resistance in cancers." (PMID 34081626, 2021). "Notably, strong colocalization was observed in tumour tissue from the control group, whereas sanguinarine treatment significantly altered the subcellular localization of p‐STAT3‐Tyr and especially p‐STAT3‐Ser, and potently inhibited the colocalization of HIF‐1α/p‐STAT3‐Tyr and HIF‐1α/p‐STAT3‐Ser." (PMID 32065498, 2020). "Finally, the expression of miRNA-18a/HIF1A/PVT1 was validated in both cell lines and clinical tumor samples by utilizing quantitative polymerase chain reaction (qPCR) analysis, which could be used as potential biomarkers for early diagnosis and target for treatment." (PMID 32226492, 2020). "Additionally, a recent study showed that HIF-1α can promote the expression of pyruvate dehydrogenase kinase 4(PDK4), further inducing macrophages polarize to M1 phenotype, which was described as a pro-inflammatory phenotype and tends to inhibit tumor progression." (PMID 32928258, 2020). "Meanwhile, they proved that HIF1α could directly regulate IL-9 expression by binding to the IL-9 promoter, and SIRT1-mTOR-HIF1α signaling-coupled glycolytic pathway positively regulated Th9 cell differentiation in vitro and in mouse tumor and allergic pulmonary inflammation models." (PMID 32377533, 2020). "However, targeting HIF1-α may not be necessary due to variable basal HIF1-α levels depending on the tumor." (PMID 33182737, 2020).
tumor (continued). "In addition, transcriptional factor hypoxia-inducible factor 1 subunit alpha (HIF1A/HIF1α)-mediated BNIP3L upregulation is required for hypoxia-induced mitophagy, indicating a potential role of BNIP3L-mediated mitophagy in hypoxic tumor microenvironments (TMEs)." (PMID 33262988, 2020). "Among these TFs, HIF1A induces the up‐regulation of PD‐L1 under hypoxic conditions and it could bind to the transcriptionally active hypoxia response element (HRE) in the PD‐L1 proximal promoter, which means that some TFs could play key role in tumor immunotherapy." (PMID 32815653, 2020). "In addition, HIF-1α expression was independent of patient’s age (P = 0.206) and CA-125 levels (P = 0.957) as well as of histological grade (P = 0.892) and subtype of the tumor (P = 0.952)." (PMID 31437208, 2019). "Although we did not measure HIF-1α expression in our samples, we speculate that both miR526b and miR655 target this pathway, resulting in VEGF secretions into the tumour microenvironment, thus facilitating tumour-associated angiogenesis and lymphangiogenesis." (PMID 31277414, 2019). "However, at the invasive front of the tumor HAF was co-expressed with HIF-2α but not with HIF-1α." (PMID 29481555, 2018). "In the report, it was suggested that HIF-1α may regulate tumor growth by regulating ectoenzyme, ectonucleoside triphosphate diphosphohydrolase 2 (ENTPD2), and extracellular levels of 5′-AMP to promote tumor growth through shaping the microenvironment of the HCC tumor in addition to direct impact." (PMID 29955245, 2018). "However, HIF‐1α dependent VEGF increase would not be able to induce the same level of tumour angiogenesis as that found in control tumours and this could be due to the slower cell migration of AQP1 silenced endothelial cells." (PMID 29044946, 2018). "Moreover, HIF-2α (but not HIF-1α) has been shown to cooperate with a number of oncoproteins frequently deregulated in cancer, such as c-Myc, epidermal growth factor receptor, and K-Ras and promoted tumor aggressiveness, EMT and invasion." (PMID 29481555, 2018). "Therefore, differential, HIF-1α-dependent NK cell positioning within hypoxic vs. normoxic tumour regions may contribute to the lack of NK cell-derived sVEGFR1 in hypoxic areas and subsequent non-productive angiogenesis." (PMID 29150606, 2017). "Despite these observations it must be recognized that HIF-1α activity can be influenced by factors other than hypoxia, so this may also influence the correlation between CA9 or GLUT-1 expression and extrinsic markers of hypoxia such as EF5 or pimonidazole in certain tumours." (PMID 27901496, 2017). "Notably, suppression of HIF-1α through the pharmacological inhibitor digoxin resulted in suppressed tumor proliferation without affecting mouse bodyweight, indicating that targeting HIF-1α may be a valuable therapeutic tool in cells overexpressing NDUFA4L2." (PMID 28593021, 2017). "Importantly, the nuclear expression of HIF-1α was not correlated with MVD, suggesting that HIF-1α might exert its function in a cell-autonomous manner rather than by stimulating tumor angiogenesis in MPNSTs." (PMID 28558056, 2017). "Therefore, disruption of the balance between HIF-1α and HIF-2α by extracellular assaults may lead to HIF-2α-mediated oncogenic activation of target genes, contributing to cancer cell survival in stringent tumor microenvironments." (PMID 28572533, 2017). "In contrast to HO-1 inducer hemin increased HIF-1α levels, this study demonstrated that HO-1 inhibitor ZnPP reduced HIF-1α expression, indicating that HO-1 may regulate amounts of HIF-1α, and can be qualified as a targeted protein for developing anti-tumor therapeutics." (PMID 26822586, 2016). "Given the role of nuclear β-arr1 to regulate gene transcription in tumor cells upon GPCR activation, we investigated whether the enhanced nuclear recruitment of β-arr1 in ET-1-stimulated EOC cells could result in the upregulation of HIF-1α target genes, VEGF and ET-1." (PMID 26909598, 2016).
tumor (continued). "However, HIF1α is not necessarily required for tumor angiogenesis." (PMID 26000250, 2015). "However, the tanshinone- 1-driven reduction of hypoxia-induced HIF-1α accumulation could not be correlated with its effect on Stat3 in either endothelial or tumor cells." (PMID 26202747, 2015). "Treatment with a HIF-1α inhibitor alone may not be sufficient to inhibit the tumor growth." (PMID 26339797, 2015). "REST is a tumour suppressor in non-neuronal cancers of the breast, colon and lung, therefore increasing the range of pathophysiological settings were our findings might be of importance in the regulation of the HIF-1α response and glycolysis." (PMID 26647819, 2015). "Thus, we hypothesized that IMQ-induced ROS activate both the STAT3 and PI3K/Akt pathways to promote HIF-1α expression but do not increase the stability or inhibit the proteasomal degradation of HIF-1α in tumor cells." (PMID 24658058, 2014). "Hypothetically, in advanced NSCLC, the variation in HIF1A has some effect on survival, but could not as the independent prognostic factor due to other molecular factors and microenvironmental elements involved in tumor growth." (PMID 24567056, 2014). "Our results may have broad clinical implications for colon patients with HIF-1α (+)/P-gp (+) expression patterns, and combination therapies aimed at modulating HIF-1α expression in concert with standard chemotherapy regimens may provide a strategy to overcome tumor resistance." (PMID 24901645, 2014). "These interactions have been established in the context of tumor and cancer progression, but the interactions during steroid treatment are unknown to our knowledge, and a mechanism for the steroid blockage of HIF1α cytoplasm-nuclear localization is not yet understood." (PMID 25255025, 2014). "Given the first metronomic Dox likely has off-target effects beyond HIF-1α inhibition, we examined whether adding metronomic Dox to DC101 and HIF-1α knockdown increased HT1080 xenograft tumor growth delay and found that there was no significant additional effect." (PMID 22684860, 2013). "Furthermore, our study suggests the possible use of HIF1α expression as a better screening tool for the development of CRPC than other biomarkers of CRPC such as chromogranin A (CgA) or circulating tumor cells, because of its high sensitivity and negative predictive value." (PMID 23342109, 2013). "To evaluate whether the reduced tumor vascularization observed in HT29-LEF-1-ΔL also occurred in tumors of the same size, we detected microvessels by immunohistochemistry for CD31, VEGFR2 and HIF1α in 18th-day tumors of different groups that were approximately the same size (about 50 mm3)." (PMID 22639890, 2012). "So, G1 arrest would be induced in the HIF-1α-positive/pimonidazole-negative layer of a micro tumor cord, however, it is also true that a proliferation-dependent enzymatic reaction could be induced in this layer, meaning that HIF-1α-positive cells are still proliferative." (PMID 23203043, 2012). "In addition, we measured HIF1α expression in the hypoxic tumors from the rats exposed to 12.5%O2 and 15%O2 found that 12.5%O2 significantly increased HIF1α expression, but no significant change in HIF1α expression was observed in the hypoxic tumor from animals exposed to 15%O2." (PMID 21812995, 2011). "Considering several articles have been reported that HIF-1α plays an active role in tumor progression and transplantation of tumors lacking HIF into immunodeficient mice results in decreased tumor growth, we next asked whether the observed effect of TPZ has any impact on tumor physiology." (PMID 21085474, 2010). "Here we found that by stabilizing HIF-1α with CoCl2, inhibition mTOR pathway was maintained following acute high oxygen exposure on tumor cells, and this may occur through a negative feedback loop dependent on HIF-1α mediated transcriptional activation of REDD1." (PMID 19587783, 2009).
tumor (continued). "However, this is unlikely as previous studies demonstrated that inhibition of hypoxic signaling by a dominant-negative HIF-1α decreased osteolytic bone destruction and tumor burden in mice euthanized at the same time point, while a constitutively active HIF had the opposite effect." (PMID 19727403, 2009). "Interestingly the overall PFI of the subgroup of patients that have undergone suboptimal cytoreduction at primary surgery (n = 21) with tumours that stained strongly for HIF-1α was significantly worse than that of patients with tumours that stained weakly or were negative for HIF-1α (p = 0.03)." (PMID 19014607, 2008). "The HIF‐1α target genes Vegf, Snai1, and Ccng2 showed reduced expression upon nAb‐CCL2 treatment in the CD group, although this did not lead to significant tumor suppression." (PMID 41160815, 2026). "Tumor-derived lactate, transported into macrophages via MCT1, not only stabilizes HIF-1α but also induces histone lactylation, facilitating macrophage polarization independently of endogenous lactate or MPC-mediated metabolism." (PMID 40433363, 2025). "On the other hand, HIF‐1α was not affected by BPR0C261, while it inhibited the expression of VEGF‐A in tumour sections." (PMID 39757131, 2025). "(b) Direct target protein binding: OTUB1 suppressed ubiquitination of proteins (e.g., HIF-1α and RACK1) through non-catalytic binding, thereby driving tumor progression." (PMID 40469292, 2025). "Consistently, flow cytometry analysis revealed that HIF-1α inhibitor YC-1, but not the HIF-2α inhibitor TC-S 7009, significantly reduced DMF-induced upregulation of PD-L1 levels on tumor cell surfaces." (PMID 40461489, 2025). "When HIF1A was present in the tumor tissue, the EPOR expression was inducted compared to the HIF1A-negative tumors and the level was similar to that of the surrounding normal tissue." (PMID 40332447, 2025). "Overall, our data suggest that only Hif1α, and not Hif2α, plays a critical role in PRCC‐TFE3–induced tumor development in vivo." (PMID 39807625, 2025). "We next explored the expression of HIF‐1α and VEGF‐A in MTCQ1 tumours treated with or without drugs." (PMID 39757131, 2025). "In the complex tumor microenvironment (TME), HIF1α’s upregulation of VEGF and other pro-angiogenic factors not only facilitates tumor growth and invasion but also contributes to immune suppression." (PMID 39697237, 2024). "pVHL’s role is like a conductor ensuring the orchestra of HIF1A and HIF2A does not go overboard, thus influencing the production of growth factors and ultimately impacting the course of ccRCC tumor progression." (PMID 39796121, 2024). "The expression levels of nuclear HIF-1α, HIF-2α, and HIF-3α in ccRCC did not vary based on age, gender (data not shown) or between tumor grade in ccRCC." (PMID 38571885, 2024). "Increased levels of MKLN1-AS significantly reduced the inhibitory effects of sh-HIF-1α on MIA PaCa-2 cells, whereas the absence of MKLN1-AS eliminated the stimulatory effects of HIF-1α on SW1990 tumor growth." (PMID 38740637, 2024). "In contrast to our expectations, the deletion of HIF-1α in CD8 T cells, on the other hand, did not significantly impact tumor growth." (PMID 39242595, 2024). "HIF-1α and HIF-2α are a pair of structurally similar factors, but their mechanisms in regulating tumor angiogenesis are not identical." (PMID 39277981, 2024). "Meanwhile, non-transcriptional activity of HIF-1α reduces CX3CL1 degradation, while IL-15Rc reduces both HIF-1α and CX3CL1 levels in tumor cells." (PMID 38279145, 2024). "Meanwhile, tumour areas with low density or absence of small-calibre vessels were normally characterized by high GLUT1 and HIF1α expression." (PMID 38542435, 2024). "Notably, hypoxic tumor volume was negatively correlated with immunohistochemistry, which might be due to the feedback mechanism that occurred between HIF-1α and markers or genes of the tumor, or the presence of the other isoforms of HIF-1α, such as HIF-2α and HIF-3α." (PMID 37445730, 2023).
tumor (continued). "mRNA levels of HIF-1α, AhR, and of their target genes as well as of ARNT and nuclear receptor coactivator NCOA2 were determined in tumor tissues from patients in whom the tumor was promptly removed either with or without prior endovascular embolization." (PMID 37305351, 2023). "Some studies have used ρ0 tumor cell lines lacking a functional ETC; these cells fail to generate ROS signals or to stabilize HIF-1α during hypoxia." (PMID 36935009, 2023). "The expression of HIF-1α and TGF-β1, a fulcrum factor for angiogenesis and tumor progression, was not affected by chalcone 16 treatment." (PMID 36903405, 2023). "The expression of GYS1 is HIF1α-dependent, but PYGL is not consistently HIF1α-dependent; PYGL depletion impairs tumor growth, as glycogen breakdown is integral to tumor cell function and growth." (PMID 38028629, 2023). "Additionally, in an 4NQO-induced OSCC in situ mouse model, PFC@O2 significantly inhibited the tumor number and size as well as weakening the expression of the proliferative marker PCNA, which may be related to the improvement of hypoxia and downregulation of HIF-1α expression by PFC@O2." (PMID 36675491, 2023). "Cancer-associated fibroblast (CAF)-specific deletion of HIF-2α, but not HIF-1α, delayed pancreatic ductal adenocarcinoma (PDAC) tumor progression and growth, and improved survival of mice, suggesting a tumor promoting role for HIF-2α in fibroblasts." (PMID 37124241, 2023). "An interesting relation was the negative correlation between the HIF-1a/HIF-2a ratio and the Clark level, as well as the Breslow index and tumor stage." (PMID 36294785, 2022). "Although both HIF1A and EPAS1 genes were upregulated in MES1-like and MES2-like tumor cells, only EPAS1 regulon (not HIF1A regulon) was activated in both MES1-like and MES2-like cells among the top activated regulons." (PMID 35669791, 2022). "Next, we, on the one hand, found that the expression level of HIF1α was significantly correlated only with LIHC pathological stage, but not with other tumor stages." (PMID 35860430, 2022). "MRNA levels of CA12 exhibited positive correlations with those of HIF1A, TNF-A, IL-10, and IL-1B, but not those of IL-6, in tumor-derived monocytes." (PMID 35362480, 2022). "An in vitro study using patient-derived xenograft recurrent GBM models demonstrated that treatment with TMZ induces HIF-1α and HIF-2α expression that coincides with real-time observation of de-differentiation of non-GSC tumor cells to stem-like cells." (PMID 35954407, 2022). "Although HIF-1α, PGK1 and VEGF tended to be lower in tumours with above median ascorbate, significance was not reached." (PMID 35419292, 2022). "In contrast, tumor cells expressing VEGFA mRNA, along with nuclear HIF-1α, were found in adjacent, but not vascular, lesions." (PMID 35392912, 2022). "We found a significant increase in the expression of hypoxia-related genes such as HIF-1α, BNIP3, and CA-IX with an increase in the number of days of tumor spheroids development as compared to non-tumorigenic spheroids." (PMID 35837091, 2022). "The data obtained from these tumours are also consistent with an upregulation of anti-angiogenic ING4 mRNA levels in the human xenograft tumours in vivo, with no significant changes are detected for ANG, VEGFA, HIF1α, THBS2 and COL18A1." (PMID 35513564, 2022). "OCUM‐12‐CM did not induce ASPN, inflammatory cytokines, HIF‐1α, IDO‐1, or KYNU expression in NFs in vitro, suggesting changes to the tumor would reflect the effects of the coinjected CEFs." (PMID 34379869, 2022). "The lack of E-cad can induce carcinogens activating Wnt, TGF-β, HIF-1α, and other signaling pathways to promote EMT, which is a reason that EMT affects tumor metastasis." (PMID 35518787, 2022). "More importantly, we found a significant negative correlation between NaCT and HIF1α expression in human HCC, suggesting that citrate can be potential therapeutic strategy preventing metabolic adaptation to hypoxic tumor." (PMID 35884416, 2022).